Y_RNA (Y RNA )
Gene: Miscellaneous RNA gene on chromosome 19 (40,339,059 to 40,339,164, reverse strand). Ensembl gene ENSG00000207281.
Homologues: Orthologues: chimpanzee Y_RNA (99% identical). Paralogues in human: Y_RNA (82% identical), Y_RNA (81% identical), RNY3 (80% identical), Y_RNA (80% identical), Y_RNA (79% identical), Y_RNA (78% identical), RNY3P1 (77% identical), RNY3P4 (77% identical), Y_RNA (77% identical), Y_RNA (76% identical), Y_RNA (75% identical), RNY3P11 (75% identical), and 87 more.